RUNX1T1 (RUNX1 partner transcriptional co-repressor 1)
Diseases named in the same sentence as RUNX1T1 in open-access papers (continued):
Sharing a sentence is not in itself a finding about the gene and the disease.
gastric cancer (2 papers, 2016 to 2022). A primary or metastatic malignant neoplasm involving the stomach. "EMSA with nuclear extracts from MKN28 and MKN45 gastric cancer cell lines transfected with increasing amounts of RUNX1t1 showed that RUNX1t1 caused a dose-dependent decrease of C/EBPβ binding to its DNA consensus sequence." (PMID 27522676, 2016). "In any case, we show that in gastric cancer development, high expression of C/EBPβ leads to reduction of RUNX1t1 expression and loss of RUNX1t1 may support unrestrained C/EBPβ function and repression of differentiation genes, including TFF1." (PMID 27522676, 2016). "Expression of RUNX1t1 protein was evaluated by tissue microarray immunohistochemistry on 64 human gastric cancer samples." (PMID 27522676, 2016). "All endogenously expressed C/EBPβ isoforms in both gastric cancer cell lines were co-precipitated with RUNX1t1." (PMID 27522676, 2016). "The RUNX1t1 promoter was frequently hypermethylated and ectopic expression of RUNX1t1 in gastric cancer cells inhibited proliferation and enhanced TFF1 expression." (PMID 27522676, 2016). "Ectopic expression of RUNX1t1 reduced proliferation in gastric cancer cell lines and counteracted the repression of TFF1 by C/EBPβ." (PMID 27522676, 2016). "However, according to observations of human gastric cancer samples, RUNX1T1 is commonly methylated, probably worsening the situation." (PMID 35902872, 2022). "In 3 out of 10 cases, we found a convincing inverse correlation between low RUNX1t1 and high C/EBPβ expression; however, the data may also suggest alternative routes of RUNX1t1 down-regulation in gastric cancer." (PMID 27522676, 2016). "In order to determine whether RUNX1t1 down-regulation in gastric cancer cells has functional consequences on cell multiplication, we rescued RUNX1t1 expression and evaluated proliferation by BrdU incorporation." (PMID 27522676, 2016). "The RUNX1t1 promoter was found to be frequently hypermethylated in human gastric cancer cases." (PMID 27522676, 2016). "Sequencing of RUNX1t1 from 26 gastric cancer patients failed to disclose mutations that would explain loss of RUNX1t1 protein (data not shown); however, analysis of the RUNX1t1 promoter revealed hypermethylation in 10 out of 20 gastric cancer DNA samples." (PMID 27522676, 2016). "Down-regulation of RUNX1t1 during homeostasis and in intestinal-type gastric cancer may initially occur through C/EBPβ; however, analysis of DNA methylation showed that the RUNX1t1 promoter was frequently methylated in human gastric cancer samples." (PMID 27522676, 2016). "When RUNX1T1 combines with C/EBPβ, its binding with DNA and repression of the TFF1 promoter gene are significantly interrupted, which reduces the proliferation of gastric cancer cell lines and slows oncogenesis." (PMID 35902872, 2022). "It was also important to examine the expression of FOG2, SPARCL1, and RUNX1t1 in normal human gastric mucosa, as no matching normal tissue samples were available from the initial human gastric cancer microarray analysis." (PMID 27522676, 2016).
small cell lung carcinoma (2 papers, 2021 to 2024). Small cell lung cancer (SCLC) is a highly aggressive malignant neoplasm, accounting for 10-15% of lung cancer cases, characterized byrapid growth, and early metastasis. "Moreover, RUNX1T1 knockdown inhibits the viability of PAX3-FOXO1 fusion-driven rhabdomyosarcoma and MYC-driven small cell lung cancer cells." (PMID 38992040, 2024).
Bone marrow failure (1 paper, 2018). "The strategy of analysis that we followed gave the proof that RUNX1T1 expression dysregulation was the cause of the bone marrow failure in these two patients." (PMID 29344089, 2018).
colon cancer (1 paper, 2017). "In pathological condition, RUNX1T1 is shown to promote microglial proliferation by regulating CDK4, but represses the proliferation and increases 5-flurouracil (5-FU) sensitivity in a colon cancer cell line (HCT116)." (PMID 28640846, 2017).
gastric tumor (1 paper, 2016). "To further assess the connection between C/EBPβ and down-regulation of RUNX1t1 in gastric tumors, we selected tumor-RNAs showing reduced levels of RUNX1t1." (PMID 27522676, 2016). "Within this signature, the RUNX1t1 tumor suppressor transcript was down-regulated in 38 % of gastric tumor samples." (PMID 27522676, 2016).
germinoma (1 paper, 2010). A malignant germ cell tumor arising in the central nervous system. "In the germinoma group, the expression levels of RUNX1T1 and THRB were inversely correlated with expression of miR-146a, and the levels of NRP1, SVIL and PDGFRA were inversely correlated with the expression of miR-142-5p." (PMID 20178649, 2010).
hepatocellular carcinoma (1 paper, 2023). A malignant tumor that arises from hepatocytes. "screened potential autoantibody-based markers for hepatocellular carcinoma (HCC) and found that the AUC of an immunodiagnostic model including 6 TAAbs (RAD23A, CAST, RUNX1T1, PAIP1, SARS, PRKCZ) were 0.835 and 0.788 in the training and validation sets, respectively." (PMID 37251926, 2023).
ischemia (1 paper, 2017). A hypoperfusion of the BLOOD through an organ or tissue caused by a PATHOLOGIC CONSTRICTION or obstruction of its BLOOD VESSELS, or an absence of BLOOD CIRCULATION. "Therefore, the discovery and application of pharmaceutical activators for RUNX1T1 will improve therapeutic efficacy toward ischemia by promoting neovascularization." (PMID 28640846, 2017).
leukocytosis (1 paper, 2024). "There was marked leukocytosis in all the patients, with a mean value of 71.43 ± 37.93, a range of 35-150 × 109/L, and a p-value of 0.0002 suggestive of marked leukocytosis in positive AML-M2 with RUNX1/RUNX1T1 patients." (PMID 39735012, 2024).
liver cancer (1 paper, 2021). An epithelial or non-epithelial malignant neoplasm that arises from the liver. "The corresponding genes of middle-stage CNV events including MYC, CNBD1, HEY1, RUNX1T1, CDH17, high expression of HEY1 gene promotes self-renewal of tumor stem cells, especially in liver cancer." (PMID 34453042, 2021).
liver disease (1 paper, 2024). "A subsequent genome-wide association study (GWAS) identified shared single-nucleotide polymorphisms (SNPs) in the genes AR, EDIL3, MACROD2, PCSK5, RUNX1T1, TENM4, and ZEB2 between PN and liver disease from the FinnGen cohort." (PMID 38397136, 2024).
meningioma (1 paper, 2016). A generally slow growing tumor attached to the dura mater. "The tumor suppressor RUNX1T1 expression was lower in meningiomas grades I and II compared to that of the controls (−4 fold, RT-qPCR)." (PMID 26950155, 2016). "It is likely that other miRNAs that can target RUNX1T1 are expressed in meningioma and could be involved." (PMID 26950155, 2016). "Low expression of the tumor suppressor RUNX1T1, in concert with the expression of p63 and Cyclin D1 could be contributing factors to the tumor growth in the non-anaplastic meningiomas." (PMID 26950155, 2016).
metabolic syndrome (1 paper, 2024). A cluster of metabolic risk factors for CARDIOVASCULAR DISEASES and TYPE 2 DIABETES MELLITUS. "Such as, it has been shown that SNP rs34269950 in the RRACH genome, located in the 3′UTR of RUNX1T1, is significantly regulated by FTO in rural populations in the Caucasus region of Australia, providing important clinical evidence for the association of m6A with metabolic syndrome." (PMID 38562618, 2024).
myeloproliferative disease (1 paper, 2014). "The knock-in model of RUNX1/RUNX1T1 under the control the Sca1 promoter induced a myeloproliferative disease, suggesting that targeting the “correct” stem/progenitor cell is important for the transformational potential of RUNX1/RUNX1T1." (PMID 25568664, 2014).
pancreatic endocrine tumors (1 paper, 2020). "RUNX1T1 mutations were shown to be predictive for the development of liver metastases from pancreatic endocrine tumors." (PMID 33400739, 2020).
Pancytopenia (1 paper, 2018). An abnormal reduction in numbers of all blood cell types (red blood cells, white blood cells, and platelets). "We report here two further patients with non-hereditary BM failure, with diagnosis of SAA and pancytopenia, respectively, caused by two different constitutional structural anomalies involving chromosome 8, and leading to the disorder due to effects on the RUNX1T1 gene." (PMID 29344089, 2018).
tumor (57 papers, 2010 to 2025). "Loss of one functional allele of Runx1t1 (Runx1t1+/−) almost completely abolished tumor development in Th-MYCN+/+ homozygous mice." (PMID 38992040, 2024). "By binding to the promoter of CDKN1A, RUNX1T1 inhibits histone acetylation, which leads to E2F upregulation and carcinogenesis acceleration, an expected modulation accompanying the loss of tumor-repressor RB1 in SCLC." (PMID 35902872, 2022). "When it comes to CRC, however, RUNX1T1 is proven to be a tumor-suppressive gene, the re-expression of which causes a significant decrease in CRC cell growth and proliferation as well as increased sensitivity to 5-flurouracil." (PMID 35902872, 2022). "Immunostaining of KELLY tumor samples excised at seven days confirmed loss of RUNX1T1 following its knockdown, as well as decreased cell proliferation as indicated by a reduced Ki67 proliferative index (47.5 ± 4.4% in knockdown tumors compared to 80.4 ± 4.3% in control tumors; P = 0.029)." (PMID 38992040, 2024). "We observed significantly higher expression levels of RUNX1T1 in leukemic cells than in cells from the tumor microenvironment (TME)." (PMID 40707954, 2025). "He and colleagues reported RUNX1T1 amplification in the SCLC compartment of patients with mixed tumor histology of both SCLC and non–non-small-cell lung cancer." (PMID 38992040, 2024). "To determine if the genomic binding of HA-tagged RUNX1::RUNX1T1 is altered due to the loss of Mga, we performed CUT&RUN on GFP+ sorted tumor cells isolated from the spleen." (PMID 38454121, 2024). "Nevertheless, it is noteworthy to highlight that within the context of GC, the gene RUNX1T1 exhibits a suppressive role, wherein it actively hinders the tumour‐promoting activity of C/EBPβ and restrains tumour proliferation." (PMID 38894657, 2024). "Taken together, these findings implicate Runx1t1 as a potential modifier responsible for the increased tumor penetrance in 129/SvJ Th-MYCN mice." (PMID 38992040, 2024). "Mice with wild-type Runx1t1 (Runx1t1+/+) had 92% tumor incidence (93/101), as expected on this background, while Runx1t1 haploinsufficiency decreased tumor incidence to 6.5% (10/163)." (PMID 38992040, 2024). "This latter locus harbors Runx1t1 and interestingly, the expression of Runx1t1 was upregulated in 129/SvJ mice compared to another strain of mice (FVB) with a reduced tumor penetrance." (PMID 38992040, 2024). "To address the molecular characteristics of tumor-reactive T cells in AML with RUNX1::RUNX1T1, we compared the transcriptional regulon and gene expression profile between tumor-reactive T cells and bystander T cells." (PMID 39243082, 2024). "We used chromogenic RNAscope in situ hybridization to detect RUNX1T1 mRNA expression in four tissue cores taken from different regions of the tumor." (PMID 33084222, 2021). "Further RNAscope analysis of an additional c‐SCLC tumor specimen also found significantly higher RUNX1T1 mRNA expression in the SCLC component compared with the NSCLC component." (PMID 33084222, 2021). "The level of RUNX1T1 mRNA expression in the SCLC component of the tumor, detected as red dots, is noticeably higher than that observed in the NSCLC component." (PMID 33084222, 2021). "We further show higher expression of RUNX1T1 in the SCLC component of another c‐SCLC tumor by in situ hybridization." (PMID 33084222, 2021). "We did, however, obtain tumor tissue from a third c‐SCLC tumor to validate RUNX1T1 expression in SCLC." (PMID 33084222, 2021). "RUNX1T1 has the ability to inhibit the growth of tumor cells and can be used to predict cancer metastasis based on its reduced expression." (PMID 32266223, 2020).
tumor (continued). "Based on our findings in co-expression networks, expression interaction of miR-15a and RUNX1T1 pair will lead to cancer transcriptional disorders, as well as encourage tumor cell growth and invasion." (PMID 32266223, 2020). "The results obtained in our study in combination with published reports support that MSH6 and RUNX1T1 have oncogenic and tumor suppressive functions respectively in cancers." (PMID 29046615, 2017). "Prior studies had revealed crucial roles for Bcl11a in regulating blood development and diseases, and for Runx1t1 in midgut development and neoplasias of blood, lung and breast." (PMID 25330008, 2014). "Whether tumor recurrence is related to mutations in MKNK1, POLE, RET, RTEL1, RUNX1T1, TAP1 still requires further research for validation." (PMID 40901169, 2025). "These suggested that the characteristic of ADGRG1 as a marker for tumor-reactive T cells not only presented in RUNX1::RUNX1T1 positive AML but also might be a common feature of tumor-reactive T cells in AML." (PMID 39243082, 2024). "In contrast, high protein levels of both MYCN and Runx1t1 were only observed in tumor samples." (PMID 38992040, 2024). "Again, a positive RUNX1T1 mRNA signal was detected as red dots on the tumor sections." (PMID 33084222, 2021). "The combination of differentially abundant miRNAs, controlling the RUNX1T1 gene, included miR-4762-5p more abundant in the IS group that might in this case act as a tumor suppressor miRNA." (PMID 34157951, 2021). "Additionally, we also compared RUNX1T1 expression in tumor specimens using RNA‐Seq data from a SCLC genomics study and the TCGA." (PMID 33084222, 2021). "Within this signature, repression of RUNX1t1 stood out as a potential tumor suppressor event." (PMID 27522676, 2016). "Thus, inhibition of RUNX1T1 by reversing the effects of PRC2 may similarly restore anti-tumor immunity in this disease and further studies of this using immunocompetent models are warranted." (PMID 38992040, 2024). "Thus, RUNX1T1 expression was significantly higher in the SCLC component of a third c‐SCLC tumor." (PMID 33084222, 2021). "However, among the class III gene mutation testing results, the genes with higher abundance mutations include MKNK1, POLE, RET, RTEL1, RUNX1T1, TAP1, indicating that these gene mutations may be related to sex-cord-stromal tumors or require further research to explore unknown tumor subtypes." (PMID 40901169, 2025). "Surprisingly, leukemic blasts were completely depleted 14 days after CD19 CAR-T cell infusion, including CD19-positive tumor cells, and the levels of RUNX1::RUNX1T1 fusion gene decreased from 327.64% to 144.82%." (PMID 40761794, 2025). "To evaluate the characteristics of tumor-reactive T cells, we collected bone marrow (BM) T cells from newly diagnosed AML patients with RUNX1::RUNX1T1 as examples for paired single-cell RNA sequencing and single-cell V(D)J sequencing." (PMID 39243082, 2024). "The Th-MYCN+/−; Runx1t1+/+ mice displayed 9.9% tumor incidence (18/181), as compared to 0.87% (3/343) in Th-MYCN+/−; Runx1t1+/− mice." (PMID 38992040, 2024). "To explore the heterogeneity of T cell compartment and the characteristics of tumor-reactive T cells, we collected BM T cells from 5 newly diagnosed AML patients with RUNX1::RUNX1T1 and performed scRNA-seq and scV(D)J-seq." (PMID 39243082, 2024). "By drawing on experiences from solid tumor research, we identified tumor-reactive T cells with unique phenotypes in AML, especially AML with RUNX1::RUNX1T1, and detected ADGRG1 as their marker." (PMID 39243082, 2024). "In the tumor tissue of AML patients, the presence of RUNX1::RUNX1T1 and CBFB::MYH11 fusions positively affects the course of the disease." (PMID 38392574, 2024).
tumor (continued). "RUNX1T1 expression was enriched in SCLC compared with all other cancers, including NSCLC, in both cell lines and tumor specimens, as shown by mRNA level and western blotting." (PMID 33084222, 2021). "Lastly, we measured RUNX1T1 mRNA expression in tissue microarrays (TMA) containing SCLC and NSCLC patient tumor cores by chromogenic RNAscope in situ hybridization." (PMID 33084222, 2021). "Then we analyzed the correlation between transcription level of CCNE1, E2F1, ARHGAP11A, RUNX1T1, FES and tumor stage in TCGA NSCLC cohort by GEPIA 2 online website." (PMID 33613291, 2021). "The results demonstrated that the expression levels of CCNE1, E2F1, ARHGAP11A, RUNX1T1 and FES displayed significant correlation with the tumor stage in patients with NSCLC." (PMID 33613291, 2021). "Furthermore, a survival analysis was conducted on the individual genes comprising the UBE2C+ tumour cell score, and it revealed statistically significant results for ITPRIP, GJA1, RUNX1T1, CD82, PAPSS2 and ANXA5." (PMID 38894657, 2024). "We did not have any additional tumor specimen to validate RUNX1T1 amplification or expression in our original two c‐SCLC tumors." (PMID 33084222, 2021). "Therefore, our results indicated the existence of tumor-reactive T cells (pTRTs and pTRT-relevant cells) in the BM of AML patients carrying the RUNX1::RUNX1T1 which showed a continuous spectrum of differentiation from the stem-like cluster to the terminally differentiated cluster." (PMID 39243082, 2024). "Though AML with RUNX1::RUNX1T1 patients were used as an example to explore, we also obtained consistent conclusions in other AML subtypes, suggesting that ADGRG1 could become a potential unified marker of CD8+ tumor-reactive T cells within AML." (PMID 39243082, 2024). "GEPIA analysis showed a significant lower expression of RUNX1T1 and HHIP in the tumor samples (n = 163) compared to the normal tissues (n = 207)." (PMID 34157951, 2021).